TNF (tumor necrosis factor)
Diseases named in the same sentence as TNF in open-access papers (continued):
Sharing a sentence is not in itself a finding about the gene and the disease.
acute coronary syndrome (47 papers, 2010 to 2026). Signs and symptoms related to acute ischemia of the myocardium secondary to coronary artery disease. "Compared to stable CAD and healthy subjects, acute coronary syndromes are associated with long-term increases in serum concentrations of anti- and pro-inflammatory cytokines, such as IL-2, IL-10, and TNF." (PMID 38541966, 2024). "TNF-α has been implicated in myocardial dysfunction resulting from acute coronary syndrome and high levels of IL-1 and IL-6 have been associated with subclinical atherosclerosis." (PMID 25374442, 2014). "Tumor necrosis factor (TNF)-α has been implicated in myocardial dysfunction resulting from acute coronary syndrome, and high levels of C-reactive protein (CRP) and interleukin (IL)-6 have been associated with subclinical ATS." (PMID 23029393, 2012). "TNF-α, abundantly expressed in unstable atherosclerotic plaques, exacerbates local inflammation by activating endothelial cells and recruiting immune cells, thereby promoting plaque vulnerability and increasing the risk of rupture that precipitates acute coronary syndrome (ACS)." (PMID 41511355, 2025). "There is clinical evidence supporting the prognostic value of CRP and IL-6 in acute coronary syndrome; however, the relevance of IL-1β and TNF-α as prognostic markers in this context remains uncertain." (PMID 40168324, 2025). "Specifically, elevated concentrations of proinflammatory cytokines, such as interleukin-1 beta (IL-1β), tumor necrosis factor-alpha (TNF-α), and interferon-gamma (IFN-γ), are associated with the increased risks of acute coronary syndrome." (PMID 39201047, 2024). "Nicorandil suppresses the inflammatory cytokines IL-1β, IL-1, IL-6, IL-10, IL-18, IL-19 and TNF-α in acute coronary syndrome patients." (PMID 34595611, 2023). "It has been found to be significantly expressed in the conditions of acute coronary syndrome by acting on TNF-α, Toll-like receptors (TLR) and transcription factor NF-κb." (PMID 36071532, 2022). "Several cytokines (tumor necrosis factors alpha [TNF-α], interstitial interleukins 1 [IL-1], chemokines, adipokines, and interferons) are involved in the occurrence of acute coronary syndrome (ACS)." (PMID 34231707, 2021). "A subset of CD4+ T-cell lacking CD28 expression (representing 5–23% of all CD4+ T-cells) and producing high levels of IFNγ and tumor necrosis factor (TNF)α have been found in the plaques from patients with acute coronary syndrome (ACS)." (PMID 33297441, 2020). "TNF-α was mostly expressed in human coronary atherosclerotic lesions, and the expression level of TNF-α was remarkably high in patients with acute coronary syndrome." (PMID 31780868, 2019). "The level of inflammatory cytokine TNF-α was remarkably high in patients with acute coronary syndromes and was related to the pathogenesis of coronary atherosclerosis and coronary plaque ruptures." (PMID 31780868, 2019). "TNF-α is an independent risk factor for CHD, which can be used to predict the stability of coronary atherosclerotic plaques and the severity of acute coronary syndrome." (PMID 26398523, 2015). "Transcriptomic profiling further indicated that TNF-α elicited distinct gene-expression programs in cells from acute coronary syndrome versus healthy donors, with differential enrichment of pathways involved in leukocyte and lymphocyte regulation, adaptive immunity, and cytokine signaling." (PMID 41596430, 2026). "Interestingly, among patients with acute coronary syndrome, all three inflammatory markers were significantly higher in individuals with the CG and GG genotypes compared with CC carriers, and TNF-α levels were greatest in those with the GG genotype." (PMID 41452882, 2025). "Another report showed that ticagrelor could reduce interleukin-6 (IL-6) and tumor necrosis factor-α (TNF-α) levels in diabetic patients with acute coronary syndrome (ACS)." (PMID 36684601, 2022).
acute coronary syndrome (continued). "An intracellular kinase is an important mediator of the inflammatory signaling cascade which is responsible for the activation of cytokine (tumor necrosis factor-alpha (TNFα), interleukin-1, IL-6) production as well as cyclooxygenase 2 and metalloproteinases during acute coronary syndrome." (PMID 34829992, 2021). "There are several studies on the relationship between the expression of TNF-α and IL-1β with secondary ventricular arrhythmias in patients with acute coronary syndromes, in which TNF-α and IL-1β are significantly upregulated and the levels increase with the deterioration of ventricular arrhythmia." (PMID 29744364, 2018). "Consequently, TNF-α and IL-1β are helpful in predicting the occurrence of secondary ventricular arrhythmia in patients with acute coronary syndrome and could be applied as useful biomarkers in estimating the severity of ventricular arrhythmia." (PMID 29744364, 2018). "RSV has been demonstrated to impact the adaptive immune response, as indicated by a reduction in the expression of TNF-α and interferon gamma (IFN-γ) in lymphocytes in individuals diagnosed with acute coronary syndrome." (PMID 40430469, 2025). "In another study, patients in the acute phase of TTS had higher concentrations of interleukins 2, 4, 10, TNF-α, IFN-γ, and EGF, but lower levels of interleukin 6 compared to individuals with acute coronary syndrome." (PMID 34738019, 2021). "Researchers in a recent study reported that OX40 expression was upregulated on CD4+CD28− T cells in patients with acute coronary syndrome and that the secretion of IFN-γ and TNF-α was suppressed by OX40 blockade." (PMID 28320444, 2017). "The effect of other acute phase reactants such as TNF, CRP and IL6 in prognosis of acute coronary syndromes is also known." (PMID 22811936, 2012). "The normal value of TNF-α in acute coronary syndrome (ACS) patients is not universally fixed, but studies show that TNF-α levels are significantly elevated in ACS compared to healthy controls." (PMID 41511355, 2025). "Proinflammatory cytokine TNF-α inhibited the overexpression of SDF-1α, and the therapy to increase SDF-1α expression may be beneficial for acute coronary syndromes." (PMID 31780868, 2019). "The proinflammatory cytokine TNF-α inhibited the overexpression of SDF-1α, and the therapy to increase SDF-1α expression may be beneficial for acute coronary syndromes." (PMID 31780868, 2019). "The current study indicates that PAPP-A expression in human PBMCs may be regulated by CRP and TNF-α through the NF-κB pathway, a mechanism that may play a critical role in increases in serum PAPP-A levels during acute coronary syndrome (ACS)." (PMID 22997483, 2012). "Moreover, in those with acute coronary syndrome (ACS), sAXL levels are significantly elevated compared to healthy controls and show a positive correlation with inflammatory markers such as high-sensitivity C-reactive protein (hs-CRP) and tumor necrosis factor-alpha (TNF-α)." (PMID 40933570, 2025).
infarction (47 papers, 2008 to 2026). A localised pathological necrosis of tissue resulting from obstruction of the blood supply usually by a thrombus, an embolus, or vascular torsion. "In addition, levels of pro-inflammatory factors, including TNF-α and IL-1β, reflected the presence of infarction associated-aseptic inflammation." (PMID 36514154, 2022). "In animals, suppression of the TNF-α/NF-κB cascade was able to decrease fibrosis, post-infarction, and remodeling with a better outcome." (PMID 41590667, 2026). "Results showed that AM-SB significantly reduced infarction volume, inflammation (IL-1β, TNF-α), and pyroptosis-related markers (NLRP3, GSDMD, ASC, Caspase-1), while decreasing gliosis and improving cerebral metabolites." (PMID 39859214, 2025). "Resveratrol significantly reduced the volume of cerebral infarcts and neurological damage scores in cerebral ischemia/reperfusion rats, significantly lowering levels of myeloperoxidase, TNF-α, and upregulating p-Akt expression." (PMID 40823184, 2025). "The current review examines the ambivalent role of inflammation (mainly TNFα-related) and cardiac macrophages (Mφ) in pathophysiologies from non-infarction origin, focusing on the protective signaling processes." (PMID 35406812, 2022). "The cytokine-mediated inflammatory response is particularly exacerbated after MI, which was well represented in our study by high values of TNF-α at the infarction area of both the sedentary and the exercised groups, after 1 week of healing." (PMID 27074178, 2016). "TNF-α in acute ischemic myocardium began to increase at 10 min after infarction, reached a climax at 20–30 min, and recovered gradually then." (PMID 21584281, 2011). "The study showed that expression of TNF-α in AMI group increased markedly by 10 min after infarction, reached a climax at 20–30 min, and recovered gradually then." (PMID 21584281, 2011). "An increased serum level of some proinflammatory cytokines, such as TNF, has been detected in atherosclerotic events, including infarction and angina." (PMID 21875436, 2011). "Serum concentrations of IL-1β and TNF-α are typically in the low pg/ml range, with increases in serum concentrations found in post-infarction and diabetic patient (values ranging between 10–25 pg/ml)." (PMID 19032770, 2008). "However, TNF-α has played a dual role in coronary microembolization, also leading to delayed protection against infarction." (PMID 40512240, 2025). "On top of that, the infarction and myocardial injury also result in activation of the complement system and production of inflammatory cytokines including interleukin-1 (IL-1), interleukin-6 (IL-6), and tumor necrosis factor-α (TNF-α)." (PMID 35578329, 2022). "Another possibility is that the myocardial injury during infarction activates the immune system which may result in the elaboration of TNFα." (PMID 35938295, 2022). "Furthermore, the serum levels of proinflammatory cytokines, including IL-6 and TNF-α, were significantly higher in the large-infarction group compared to the control group." (PMID 33375339, 2020). "Regarding the role of the NF-kB signalling pathway, we hypothesized that its participation in the pathogenesis of AMI may also be related to CD4-expressing T cells, TNF-α and IL-10 in myocardial ischaemia and infarction." (PMID 32332808, 2020). "Whether in the control group or the infarction group, the level of sRAGE was negatively correlated with TNF-α and high-sensitivity C-reactive protein." (PMID 31275446, 2019). "TNF-α administration can also mimic the ischemic preconditioning and reduce infarction size, although the protective effects of TNF-α may only occur with low doses, but not higher doses." (PMID 30510628, 2018). "In addition to the reduced expression of proinflammatory cytokines, statins also improve the balance between TNF-α and IL-10 in postmyocardial infarction in rats." (PMID 30524484, 2018).
infarction (continued). "The expression levels of inflammatory cytokines TNF-α, IL-1β, and CCN1 in the peri-infarction cortex showed an increase post-I/R, a decrease post-TGN-020 treatment, and a subsequent increase following ERK1/2 pathway activation." (PMID 37695472, 2024). "We monitored the mRNA levels of IL-1β, TNF-α, IL-6 and MCP-1 in border zone of left ventricular infarct by RT-PCR." (PMID 31164920, 2019).
abscess (46 papers, 2009 to 2026). An inflammatory process characterized by the accumulation of pus within a newly formed tissue cavity which is the result of a bacterial, fungal, or parasitic infection or the presence of a foreign body. "At univariate logistic regression, age at surgery, age at diagnosis, disease location, history of perianal fistula or abscesses and previous long-term use of steroids, anti-TNFα or mesalamine were found significantly associated with recurrence risk." (PMID 35879620, 2022). "On the other hand, a relationship has been identified between low producer allele of TNF-α and symptomatic abscess." (PMID 28210435, 2017). "Because neutrophilic abscess formation is a hallmark of immunity against S. aureus skin infections, we next asked whether TNF and TNFR signaling affected neutrophil recruitment during the S. aureus skin infection." (PMID 37327341, 2023). "Other preoperative management like weaned-off corticosteroids, azathioprine, and anti-TNF-α agents, and abscess/fistula drainage may be also linked to the low rate of postoperative morbidity." (PMID 26200619, 2015). "In murine models, PIX (30 mg/kg i.v.)reduced inflammatory markers (CRP, IL-6, TNF-α), abscess size, and bacterial loads to levels comparable with ΔhisD infection." (PMID 41294339, 2026). "In vivo, pixantrone (30 mg/kg) decreased serum CRP, IL-6, and TNF-α levels while diminishing abscess sizes and splenic bacterial loads (P < 0.05 vs. untreated)." (PMID 41294339, 2026). "This interpretation aligns with the known role of TNF-α and IL-1β in abscess wall formation and containment of infection." (PMID 41531628, 2025). "The highest mean IOD TNF-α staining was observed in samples with dysplasia, abscesses, mucin depletion and basal plasmacytosis." (PMID 40002819, 2025). "Inflammation reaction has been identified in PPV as the formation of abscesses by neutrophil and eosinophil and the presence of Interleukin-6 (IL-6), Interleukin-8 (IL-8), and Tumor Necrosis Factor-alpha (TNF-α)." (PMID 40565944, 2025). "An intraoperative abscess complicated the ileocecal resection for the two patients treated with anti-TNF before surgery, requiring a protective per operative stoma placement." (PMID 36882155, 2024). "This entails an examination under anaesthesia [EUA] with seton[s] to facilitate tract drainage and to prevent abscesses from reforming followed by anti-TNF therapy." (PMID 38491943, 2024). "IL-6 and TNF-α were significantly higher in patients in the abscess group compared with the control group (p < 0.01)." (PMID 37091905, 2023). "We present here the case of a 66-year-old male patient who presented with painful abscess-like nodules on his right hand and forearm, which worsened after treatment with an anti-TNF-a agent." (PMID 37512971, 2023). "After S. aureus skin infections, the production of proinflammatory cytokines and other inflammatory mediators (such as IL-1β and TNF) would promote neutrophil recruitment from the bloodstream to form an abscess to facilitate bacterial clearance." (PMID 37127622, 2023). "Depletion of liver-resident macrophages by clodronate-loaded liposomes abrogated abscess formation, and depletion of TNF (which is also secreted by Ly6Chi monocytes) revealed that this cytokine is mainly responsible for tissue damage." (PMID 33829283, 2021). "Following abscess drainage, the preferred CD medical treatment option is anti-TNF therapy in addition to ongoing antibiotic treatment." (PMID 33971899, 2021). "A significant reduction in abscesses and inflammatory nodules of 60% (p < 0.004) and 46% (p < 0.001) was seen in anti-TNF-naive and anti-TNF-failure groups, respectively." (PMID 33182701, 2020). "Though anti-TNF agents were used in some patients in conjunction with abscess drainage when appropriate and intravenous antibiotics, the majority of these patients still required resectional surgery." (PMID 36776501, 2020).
abscess (continued). "The high lesional MMP8 levels were accompanied by elevated blood levels that positively correlated with TNF-α blood levels and disease severity assessed by Sartorius score, especially with the number of regions with inflammatory nodules/abscesses and fistulas." (PMID 27843200, 2016). "Both anti-TNF medication and advancement plasty have been described to have up to a 50 % re-intervention rate due to recurrent fistulas or abscess formation, whereas this is hardly seen in chronic seton drainage due to preservation of a patent tract." (PMID 26289163, 2015). "TNF was also present in small numbers of macrophages and lymphocytes within areas of inflammation or at the margins of abscesses." (PMID 25719526, 2015). "At day 4 post-infection, abscess tissue of infected mice treated with NO-np contained significantly higher quantities of TNF-α, IFN-γ, IL-12, IL-1β, MCP-1, and TGF-β than that of np or untreated mice." (PMID 19915659, 2009). "Furthermore, post-drainage, there is a sharp decline in pyrogens within the abscess cavity, such as endotoxins, IL-1β, and TNF-α." (PMID 41585276, 2025). "Suppression of these cytokines by TNF-α inhibition may have impaired abscess maturation, allowing bacterial persistence and subsequent hematogenous spread." (PMID 41531628, 2025). "In healthy individuals, TNF-α is a key mediator of abscess formation in response to S." (PMID 41531628, 2025). "However, in situations where abscesses are present, we still believe that source control, with a dedicated exam under anaesthesia, remains a critical step prior to initiating anti-TNF therapy." (PMID 38491943, 2024). "Furthermore, elevated TNF-α levels lead to hyperkeratinization of follicles and eventual rupture of abscesses seen in HS." (PMID 39364517, 2024). "In addition, IL-6 and TNF-α were significantly decreased in patients in the surgical group compared with the abscess group (p < 0.01)." (PMID 37091905, 2023). "Furthermore, approximately half of Korean pediatric CD patients have perianal fistulas and/or abscesses at the time of diagnosis, which requires more potent immunosuppressants, such as anti-tumor necrosis factor-α (anti-TNF) agents." (PMID 36016153, 2022). "In the treatment of complex peri-anal fistulae due to CD an initial abscess drainage and seton placement, according to the symptoms and complexity of the fistula and anti-TNF treatment including infliximab or adalimumab can reduce fistula drainage and induce fistula closure." (PMID 33971899, 2021). "Indeed, depletion of TNF using a specific monoclonal antibody reduces abscess size in the mouse model of amebiasis." (PMID 33829283, 2021). "IL-23 injection induced skin inflammation in the ears, as demonstrated by increased histology scores of multiple parameters (inflammation, abscesses, acanthosis, ulceration, parakeratosis), as well as mRNA expression levels of IL-17A, IL-17F, IL-22 and TNFα, compared with saline treated mice." (PMID 27905482, 2016). "Furthermore, TNFα produced by the Ly6C-expressing monocytes, was found to be a cytokine that is critically involved in abscess development." (PMID 23300453, 2013). "The 11 patients with an abscess were treated with antibiotics before surgery, 4 only with enteral nutrition and antibiotics, 2 with immunosuppressants and antibiotics, 3 with enteral nutrition, immunosuppressant, and antibiotics, and 2 with anti-TNF and antibiotics." (PMID 36882155, 2024). "Previously, we demonstrated that auranofin applied topically is effective in significantly reducing the burden of MRSA in an uncomplicated abscess model in mice and in decreasing expression of pro-inflammatory cytokines (TNF-α, MCP-1, IL-1β, and IL-6) that may impair wound healing." (PMID 32350417, 2020). "The formation of inflammatory nodules, abscesses, fistulas, and sinus tracts is characterized by a large inflow of key pro-inflammatory mediators, such as IFN-γ, TNF-α, IL-1, IL-17, and IL-12/23." (PMID 35409118, 2022).